NOS2 (nitric oxide synthase 2)
Diseases named in the same sentence as NOS2 in open-access papers (continued):
Sharing a sentence is not in itself a finding about the gene and the disease.
neurodegenerative disease (6 papers, 2015 to 2023). A disorder of the central nervous system characterized by gradual and progressive loss of neural tissue and neurologic function. "Thus, drugs that inhibit Nos2 expression may be possible therapeutic agents for diseases associated with an overproduction NO, including septic shock, inflammation, and neurodegenerative diseases." (PMID 25890327, 2015). "In the present study, JQ1 inhibited both Ptgs2 and Nos2 expression, and these inhibitory effects of JQ1 may play a potential role in the treatment of neurodegenerative diseases, possibly through its inhibition of microglia and the ensuing inflammatory responses in the CNS." (PMID 25890327, 2015).
cardiovascular disease (5 papers, 2016 to 2025). "Future studies should address other cell types to provide a more comprehensive understanding of NOS2 in cardiovascular disease." (PMID 41077251, 2025). "NOS2 inhibitors and PTGS2 inhibitors have been identified for the treatment of cardiovascular disease." (PMID 34422068, 2021).
colorectal (4 papers, 2006 to 2025). "KA/KA;Nos2−/− BM-induced lung SCC in one out of five irradiated KA/KA mice and in zero out of five irradiated KA/KA;Nos2−/− mice, suggesting that macrophage NOS2 is required for lung SCC development." (PMID 29844930, 2018).
retinopathies (4 papers, 2007 to 2019). "Intercellular adhesion molecule-1 (ICAM-1 or CD54) and nitric oxide synthase 2 (NOS2) are two molecules involved in retinal disorders." (PMID 19626134, 2009).
infectious disease (2 papers, 2021 to 2025). A disorder directly resulting from the presence and activity of a microbial, viral, or parasitic agent in humans. "Further studies across diverse populations and clinical settings are needed to clarify the broader relevance of NOS2 in infectious disease susceptibility and progression." (PMID 41226345, 2025).
brain disorder (1 paper, 2024). A disease affecting the brain or part of the brain. "Others include NOS2, an important signaling molecule of the central nervous system associated with neurotransmission and diverse brain disorders, and AGTR1, which is associated with susceptibility to brain neurodegeneration." (PMID 38532526, 2024).
intestinal disease (1 paper, 2019). "The role for NOS2 in intestinal disease has been controversial." (PMID 31595002, 2019).
NOS2 also shares sentences with these, for which no sentence is quoted: Crohn disease (6 papers); atopic dermatitis (4); metabolic disorders (4); metastatic tumors (4); preeclampsia (4); chronic periodontitis (3); colonic (3); coronary heart disease (3); eczema (3); experimental autoimmune encephalomyelitis (3); lupus (3); Parkinsonism (3); Shock (3); acute myocardial infarction (2); adenocarcinoma (2); allergic disease (2); ankylosing spondylitis (2); atopic asthma (2); Behçet disease (2); bladder cancer (2); carotid atherosclerosis (2); cerebral palsy (2); chronic obstructive pulmonary disease (2); Cluster headache (2); cutaneous melanoma (2); cystic fibrosis (2); cystitis (2); gastric adenocarcinoma (2); gastric ulcer (2); Glucose intolerance (2).
A further 124 diseases each share a sentence with NOS2 in 2 papers or fewer.